HTATSF1P2 (HIV-1 Tat specific factor 1 pseudogene 2)
Gene: Processed pseudogene on chromosome 6 (3,023,142 to 3,023,772, reverse strand). Ensembl gene ENSG00000271361.
Diseases named in the same sentence as HTATSF1P2 in open-access papers:
HTATSF1P2 is named in the same sentence as 1 disease in open-access papers, as found by Europe PMC text mining. Sharing a sentence is not in itself a finding about the gene and the disease.
HTATSF1P2 shares sentences with these, for which no sentence is quoted: Obesity (1 paper).